HIF1A (hypoxia inducible factor 1 subunit alpha)
Diseases named in the same sentence as HIF1A in open-access papers (continued):
Sharing a sentence is not in itself a finding about the gene and the disease.
tumor (continued). "The increased expression of HIF-1α contributes to the recruitment of TAMs and the polarization of M2-like TAMs, resulting in enhanced tumor proliferation, migration, invasion, angiogenesis, and drug resistance." (PMID 40302816, 2025). "DBD attenuates tumor growth primarily by inhibiting HIF-1α/VEGF-mediated angiogenesis, with complementary contributions from restored immune homeostasis and ameliorated hypoxia." (PMID 41210868, 2025). "Hypoxic PCa cells release EVs enriched with oncogenic cargo, such as miR-210, miR-21, HIF1α target proteins, and long non-coding RNAs, that modulate the behaviour of recipient cells in the tumour microenvironment and distant pre-metastatic niches." (PMID 40806577, 2025). "Veillonella is known to be involved in lactate metabolism, and excessive lactate accumulation has been shown to trigger the activation of the HIF-1α, leading to enhanced tumor proliferation." (PMID 40391224, 2025). "To further analyze the downstream mechanisms by which PRCC‐TFE3 regulates tumor development via HIF1α, we performed RNA‐seq analysis on kidney tissues from TFE3‐RCC mice." (PMID 39807625, 2025). "MelCAM and HIF-1α can interact, and this interaction can influence tumor behavior, including angiogenesis and metastasis." (PMID 40869109, 2025). "TACE initiates tumor ischemia and hypoxia, leading to elevated HIF-1α and subsequent VEGF upregulation through promoter binding-mediated transcriptional activation." (PMID 41179689, 2025). "Extensive immunohistochemistry analysis of tumor specimens from various cancer types shows prevalent HIF-1α overexpression in most advanced cases, and unfavorable prognosis for patients." (PMID 39470609, 2025). "HIF-1α is recognized as a promoter of tumor progression, and substantial efforts have been directed towards developing HIF inhibitors as therapeutic agents due to their upstream regulation of VEGF." (PMID 40343532, 2025). "According to the proposed mechanism, Gln consumption by ccRCC tumor cells leads to local depletion of extracellular matrix Gln, thereby activating the HIF1α/IL-23 signaling pathway in tumor-infiltrating macrophages." (PMID 40276500, 2025). "In PCa, hypoxia induces CXCR4 expression via HIF-1α–dependent transcription, enhancing tumour cell chemotaxis toward CXCL12 (SDF-1) secreted by bone marrow stromal cells, a key mechanism promoting bone metastasis." (PMID 40806577, 2025). "Adenosine, produced in response to tumor hypoxia, is another key driver of angiogenesis, promoting HIF-1α stabilization and VEGF production through ligation of the A2AR." (PMID 41235226, 2025). "They reported EGCG reduced tumor‐induced HIF‐1α by inhibiting cancer‐induced insulin receptor (IR) and IGF1R." (PMID 40755497, 2025). "Here, we developed a network model to explore how HIF-1α mediates the adaptive response of tumor cells to hypoxia." (PMID 40171017, 2025). "HIF-1α is crucial in the response to hypoxia in the tumor and stimulates angiogenesis through induction of VEGF expression." (PMID 40649317, 2025). "Researchers have found that in pancreatic cancer patients, myCAFs often express high levels of arginase II (Arg 2), particularly in hypoxic tumor regions enriched with HIF‐1α, which correlates with poor clinical outcomes." (PMID 41164803, 2025). "This stabilization of HIF-1α enhances glycolysis and apoptosis resistance in tumor cells; Under hypoxic conditions, HIF-1α directly binds to the promoters of certain lncRNAs (e.g., H19, DARS-AS1) and induces their transcription." (PMID 40861273, 2025). "Tumor hypoxia enhances cancer aggressiveness and adversely affects prognosis via HIF‐1α‐mediated signaling enhancing angiogenesis, EMT, and metastasis." (PMID 40740483, 2025). "HIF-1α profoundly alters the composition and behavior of tumor-infiltrating immune cells, altering the immune response towards immunosuppression and tumor progression." (PMID 39981236, 2025).
tumor (continued). "In the CT26 murine colon cancer model, tumor hypoxia drove VISTA expression via HIF‐1α, which was highest in CD11bhigh Gr1+ MDSCs, and hypoxia‐induced VISTA expression in MDSCs contributed to its inhibition of T‐cell proliferation and activation." (PMID 40452814, 2025). "Previous studies have shown that HILPDA is regulated by HIF-1α and that HIF-1α functions as a transcription factor in tumor progression." (PMID 39920992, 2025). "PTEN is a tumor suppressor and phosphatase that negatively regulates phosphoinositide 3-kinases (PI3K), and its loss similarly leads to increased HIF-1α and VEGF." (PMID 41450919, 2025). "As is well known, high expression of HIF-1α enhances cellular glycolysis and promotes tumor progression." (PMID 41372134, 2025). "Hypoxia-inducible factor-1α (HIF-1α) and its signaling pathway are key mediators that enable cellular adaptation to hypoxic conditions, promote immunosuppression, and drive tumor progression and resistance to immunotherapy." (PMID 41019982, 2025). "By selectively targeting hypoxic tumor regions, HAPs reduce the viability of HIF-1α-expressing cells, alleviating the hypoxic burden on the IVM." (PMID 39981236, 2025). "Overexpression of HIF1A under hypoxic conditions further exacerbates tumour aggressiveness by promoting adaptive survival mechanisms." (PMID 41007296, 2025). "A high expression of Hypoxia-Inducible Factor 1 Alpha (HIF1A), a transcription factor inhibiting endothelial cell death in the tumour microenvironment, is the resistance to conventionally fractionated radiation therapy." (PMID 40641540, 2025). "Like the CSC markers, 5FU also caused the increase in HIF1α and VEGFA expression within the tumor niche." (PMID 40045186, 2025). "By promoting these processes, HIF-1α facilitates tumor cell proliferation, invasion, metastasis, and resistance to various therapies, ultimately contributing to cancer progression." (PMID 41585262, 2025). "Research conducted in vivo has underscored the advantageous impact of disrupting the interaction between HIF1α and p300 in terms of suppressing both target genes and, consequently, tumor growth." (PMID 40284037, 2025). "Research on the HIF-1α/ADAM10 signaling pathway in tumor occurrence and development is relatively scarce." (PMID 40563539, 2025). "RNA‐seq and metabolomic analyses of the kidney tissues from these mice revealed that ketone body production is inversely correlated with tumor development, whereas de novo lipid synthesis is upregulated through the HIF1α/SREBP1‐dependent mechanism in TFE3‐RCC." (PMID 39807625, 2025). "Unlike their similar oncogenic roles in most tumors, HIF1α and HIF2α reportedly exert opposing effects on ccRCC biology, with HIF1α acting as a tumor suppressor while HIF2α acts as an oncoprotein." (PMID 40775208, 2025). "We aim to further define the relationship that is characterized by the tumor intentionally maintaining a hypoxic environment to allow for continuous stimulation of angiogenesis via HIF1α and VEGF." (PMID 40806669, 2025). "Based on these findings, SKA3-mediated HIF-1α stabilization enhanced glycolysis, enabling tumor cells to tolerate hypoxia and thereby promoting liver metastasis in LUAD." (PMID 41298345, 2025). "Concurrently, these macrophages upregulate the HIF-1α pathway to augment tumor cell glycolytic metabolism, enabling survival within the hypoxic peritoneal niche." (PMID 40109347, 2025). "HIF-1α also modulates the tumor cell cycle, preventing cells from entering G2/M phase, which is characterized by increased radiosensitivity." (PMID 40710312, 2025). "These transcriptional effects are mediated by inhibition of HIF-1α stabilization under hypoxic conditions, which curtails the hypoxia-induced angiogenic switch in tumor microenvironments." (PMID 41226270, 2025). "Knocking down SKA3 combined with HIF-1α inhibitors (PX-478) suppressed tumor cell glucose metabolic reprogramming, weakened hypoxia tolerance, and synergistically inhibited LUAD liver metastasis." (PMID 41298345, 2025).
tumor (continued). "This revision description makes explicit that “GPR35 downregulation” leads to the inactivation of the AKT/HIF-1α signaling pathway, which in turn produces two synergistic anti-tumor outcomes: inhibition of proliferation and promotion of apoptosis." (PMID 41459506, 2025). "Mechanistically, Notch signaling activation supports the preservation of MSLCs by either inducing its downstream effector HES1 or activating HIF1α/β, promoting the upregulation of tumor-related genes such as VEGF." (PMID 40399946, 2025). "Another report suggested that the influence of EGCG on tumor size was mediated by the inhibition of HIF-1α (hypoxia-inducible factor 1α) and NFκB (nuclear factor κB) activation along with VEGF (vascular endothelial growth factor) expression." (PMID 40867905, 2025). "In the context of tumor growth and metastasis, hypoxia frequently occurs due to inadequate angiogenesis and increased tumor cell metabolism, under which HIF-1α becomes activated, facilitating tumor cell adaptation and survival." (PMID 39781344, 2025). "Tumor angiogenesis studies further revealed NF‐κB can drive VEGF expression via both HIF‐1α‐dependent and ‐independent pathways and engages in a negative feedback loop with HIF‐1α." (PMID 40981413, 2025). "In other studies, HIF-1α inhibitors have also been reported as therapeutic targets for inhibiting tumor proliferation and malignancy." (PMID 39941717, 2025). "We analyzed the tumor and surrounding healthy tissue from patients with ccRCC after radical nephrectomy to explore hypoxia-related HIF1A and EPO expression and JAK2/STAT5 signaling pathways." (PMID 40332447, 2025). "In tumor progression, HIF-1α upregulates the expression of related genes encoding all VEGF isoforms, as well as other growth factors (PlGF, FGF, PDGF, and Ang-1), promoting tumor angiogenesis and inducing resistance to drugs." (PMID 39370481, 2025). "In cancer, PRMT3 drives glycolysis by methylating LDHA and HIF1α, promoting tumor growth and immune evasion." (PMID 41583428, 2025). "HIF-1α, a pivotal regulator of aerobic glycolysis in tumor cells, not only supports tumor cell energy metabolism but also drives tumor angiogenesis by modulating the expression of angiogenic proteins, including VEGF." (PMID 40303296, 2025). "HIF-1α combines with different hypoxia response genes to provide a material basis for the continuous growth, proliferation, and metastasis of tumor cells." (PMID 40621799, 2025). "Under hypoxic conditions, Tumor cells disrupt the basement membrane in a HIF-1α-dependent manner through initiating a proteolytic cascade." (PMID 41585262, 2025). "Knockdown of transketolase also raises α-KG levels, enhancing PHD2 activity and destabilizing HIF-1α, thereby impeding tumor adaptation to hypoxia." (PMID 40931345, 2025). "In vivo studies show that RES can suppress tumor growth by 40%–50% by inhibiting the STAT3/HIF‐1α/VEGF axis." (PMID 40860906, 2025). "Cancers frequently upregulate secretion of tumor-derived exosomes (TDEs) as a result of low pH and hypoxia-induced HIF-1α-dependent activation of Rab27a, a master regulator of exosome production." (PMID 39796781, 2025). "HIF-1α facilitates the adaptation of tumor cells to hypoxic environments by activating the transcription of relevant genes." (PMID 40918147, 2025). "This reversal is achieved by VC inactivating the HIF-1α, which inhibits cell migration and invasion, thereby potentially limiting tumor progression and metastasis." (PMID 40950984, 2025). "HIF-1α emerges as one such marker - its presence not only indicates a more aggressive tumor phenotype but also suggests potential for future targeted therapies." (PMID 40546546, 2025). "Other pathways, such as JAK-STAT signalling, fatty acid degradation, and retinol metabolism, also appear to maintain cellular homeostasis and reduce tumour aggressiveness when WWOX expression is relatively high compared to HIF1A." (PMID 41007296, 2025).
tumor (continued). "The treatment of CAPE produced two separate effects which led to its outcome: (i) the decrease in tumour mass reduced hypoxic conditions and (ii) the treatment improved HIF-1α breakdown and oxygen usage efficiency." (PMID 41463127, 2025). "We further confirmed the role of HIF1A in the hypoxic tumour core, supporting its pro-metastatic role." (PMID 41007296, 2025). "The endogenous marker HIF‐1α serves as an indicator to gauge the extent of hypoxia within the tumor." (PMID 40231958, 2025). "Tumor hypoxia upregulates the expression of HIF-1α in the tumor microenvironment, which results in the recruitment and expansion of cancer-associated fibroblasts and myeloid cells into the tumor environment." (PMID 40341988, 2025). "Targeted therapies that focus on HIF-1α appear promising in EC, especially helping cancer cells adapt to low-oxygen conditions, thereby promoting tumor progression, invasion, and resistance to treatment." (PMID 39996906, 2025). "Src has been shown to be involved in multiple signaling pathways, such as PI3K/AKT and HIF1α, and to impact tumor angiogenesis, metabolism, and metastasis." (PMID 41148827, 2025). "Genetic defects in FH can lead to elevated fumarate levels, which stabilize HIF-1α and activate pathways that promote angiogenesis, further linking it to tumor progression." (PMID 40034261, 2025). "Hypoxia, a common feature of the tumor microenvironment, induces HIF-1α, which also represses MIC-A/B transcription." (PMID 40299429, 2025). "Under hypoxic conditions, HIF-1α can cause changes in Smad's structural domains, promoting the function of TGF-β and the glycolysis of tumor cells." (PMID 40696413, 2025). "Multiple studies indicate that HIF-1α suppresses NK cell-mediated tumor surveillance by inhibiting the IL-18-dependent NF-κB signaling axis, thereby attenuating anti-tumor responses." (PMID 40791591, 2025). "A significant difference was observed in the negative, low, and high expression status of PD-L1 based on the HIF-1α expression status in the tumor microenvironment (p = 0.029)." (PMID 39996842, 2025). "On one hand, it activates hypoxia-inducible factor-1α (HIF-1α), thereby transcriptionally up-regulating the expression of programmed death ligand 1 (PD-L1) on tumor cells, promoting immune escape of tumor cells." (PMID 40557160, 2025). "For instance, LncHIFCAR (formerly known as MIR31HG) activates hypoxia-related signaling pathways, such as glycolysis and metabolic reprogramming, and promotes tumor growth and metastasis by directly binding to HIF-1α to form a complex." (PMID 40861273, 2025). "This evidence underscores the molecular crosstalk between RUNX2 and HIF-1α in tumour conditions, leading to disease progression through aberrant angiogenesis, resulting in tumour vascularization and poor prognosis." (PMID 40806771, 2025). "Tumor cells increase TGF-β production through hypoxia-induced HIF-1α activity and oncogenic signaling pathways such as SMAD-dependent TGF-β autocrine loops." (PMID 40299429, 2025). "The hybrid algae-radiation-laser combination therapy system effectively suppressed tumor growth by blocking the HIF1α/VEGF axis to inhibit angiogenesis and proliferation and induce apoptosis." (PMID 39858100, 2025). "This process plays a crucial role in tumor growth and progression because HIF-1α is an important transcription factor that regulates the adaptation of tumor cells to low-oxygen conditions." (PMID 40260303, 2025). "Recent studies have found that HIF-1α can promote tumor cell survival and proliferation by regulating key points of iron metabolism to promote tumor cell resistance to ferroptosis." (PMID 41154694, 2025). "Under hypoxic conditions, NONO is upregulated as a hypoxia-inducible gene and directly binds to and stabilizes HIF-1α mRNA, thereby amplifying hypoxia signaling to promote tumor progression and angiogenesis." (PMID 41174721, 2025).
tumor (continued). "In solid tumours, metabolic alterations and stimulation of glycolytic factors are observed in the presence of HIF-1α, which helps to create a tumour microenvironment." (PMID 40806771, 2025). "HIF-1α-mediated tumor hypoxia drives angiogenesis, immune suppression, and extracellular matrix remodeling, creating an environment that promotes tumor progression and resistance to immunotherapies." (PMID 39981236, 2025). "Translational and clinical studies have demonstrated that the inhibition of HIF-1α diminishes antioxidant activity and tumor angiogenesis, modifies the TME, and increases radiosensitivity in solid tumors." (PMID 40724808, 2025). "Meanwhile, the protein level was higher in tumor tissue compared to normal tissue and, similarly, the expression level of HIF1A was higher in HCT-116 and SW-620 cells (3.78 and 17 times (p ≤ 0.05), respectively) compared to non-tumor cells." (PMID 40072116, 2025). "Under hypoxic conditions, HIF-1α accumulates owing to its oxygen-sensing capability, promoting tumour development through VEGF-dependent angiogenesis." (PMID 40806771, 2025). "FF were reported to be associated with HIF-1α, CAIX, and Glut-1 overexpression indicative of chronic hypoxia signaling in the central part of the tumor." (PMID 40362659, 2025). "HIF1A, as a core hypoxia-inducible transcription factor, has gained extensive attention for its role in tumor initiation and progression." (PMID 41198650, 2025). "Under these metabolically suppressed conditions, tumour cells regulate the expression of genes such as HIF1‐α, NF‐κB, and Notch transcription factors to undergo epithelial–mesenchymal transition (EMT)." (PMID 40525649, 2025). "In the tumor microenvironment, ROS-mediated stabilization of HIF-1α facilitates metabolic plasticity and neovascularization." (PMID 40867898, 2025). "Among the HIF-1α-positive Khasi patients, 13 cases (72%) showed higher tumor stage and a DOI greater than 5 mm." (PMID 40546546, 2025). "Hypoxia‐inducible factor‐1α (HIF‐1α), a pivotal transcription factor responsible for triggering tumour angiogenesis, is believed to be stabilised in tumours that commonly outgrow their existing blood supply and lead to hypoxia." (PMID 39757131, 2025). "A cadre of tumor-suppressive miRNAs—miR-3662, miR-199a-5p, miR-125a, miR-885-5p counter this shift by directly targeting HIF1A or the rate-limiting enzyme Hexokinase 2 (HK2)." (PMID 41007803, 2025). "In a previous study, it was confirmed that the activity of NK cells in HCC expressing HIF-1α by treatment with CoCl2 was increased due to the blocking of IL-6 in the tumor microenvironment (TME)." (PMID 40430040, 2025). "Bevacizumab enhances oxygen delivery by normalizing the tumor vasculature and reducing HIF-1α stabilization, which indirectly results in preserved epithelial junctions and the suppression of EMT-mediated invasion." (PMID 40507913, 2025). "These nanoparticles inhibit HIF-1α transcriptional activity, thereby reducing angiogenesis and tumor invasion." (PMID 40136686, 2025). "Previous studies have proven that SREBF1, GPNMB, and HIF1A can promote primary tumor growth in a variety of cancers." (PMID 40095604, 2025). "TNBCvax, which targets three key tumor-associated antigens (TOP2A, HIF-1α, and IGF-1R), offers superior tumor prevention and immunogenicity compared to single-antigen vaccines." (PMID 40969744, 2025). "The influential role of HIF-1α in multiple processes of cancer metastasis has been established based on accumulating evidence from preclinical studies, resulting in the recognition of HIF-1α as a promising therapeutic target for tumor metastasis." (PMID 40164945, 2025). "Emerging evidence reveals a complex interplay between HIF-1α and cytokine signaling pathways in the tumor microenvironment." (PMID 40791591, 2025).